RNU6-819P (RNA, U6 small nuclear 819, pseudogene)
Gene: Small nuclear RNA gene on chromosome 8 (47,131,781 to 47,131,887, reverse strand). Ensembl gene ENSG00000200986.
Homologues: Orthologues: chimpanzee U6 (99% identical), guinea pig U6 (81% identical), dog U6 (79% identical), pig U6 (70% identical). Paralogues in human: RNU6-1021P (90% identical), RNU6-127P (90% identical), RNU6-104P (89% identical), RNU6-1239P (89% identical), RNU6-1268P (89% identical), RNU6-286P (89% identical), RNU6-473P (89% identical), RNU6-617P (89% identical), RNU6-631P (89% identical), RNU6-749P (89% identical), RNU6-816P (89% identical), RNU6-848P (89% identical), and 1291 more.